ANKRD37 (ankyrin repeat domain 37)
Synonyms: Lrp2bp
Tractability: PROTAC: UniProt records ubiquitination sites on it; ubiquitination databases record sites on it.
Gene: Protein-coding gene on chromosome 4 (185,396,021 to 185,400,628, forward strand). Ensembl gene ENSG00000186352.
Subcellular location: Nucleus; Cytoplasm
Subcellular location (Human Protein Atlas): Cytosol; Nucleoplasm
Gene Ontology:
Molecular function: protein binding
Cellular component: cytosol; nucleoplasm; cytoplasm; nucleus
Genetic constraint (gnomAD): Loss-of-function variants: 17 observed, 20.16 expected, observed/expected ratio (o/e) 0.84, 90% interval 0.58 to 1.26. The upper end of that interval is the gene's LOEUF score, 1.26, which puts it in group 5 of 6, group 1 being the genes least tolerant of losing a copy. Missense variants: 207 observed, 201.68 expected, observed/expected ratio (o/e) 1.03, 90% interval 0.92 to 1.15. Synonymous variants: 79 observed, 79.57 expected, observed/expected ratio (o/e) 0.99, 90% interval 0.83 to 1.2.
Homologues: Orthologues: chimpanzee ANKRD37 (99% identical), macaque ANKRD37 (94% identical), dog ANKRD37 (86% identical), rabbit ANKRD37 (86% identical), pig ANKRD37 (81% identical), guinea pig ANKRD37 (78% identical), mouse Ankrd37 (77% identical), rat Ankrd37 (76% identical), tropical clawed frog ankrd37 (54% identical), zebrafish ankrd37 (47% identical). Paralogues in human: ANKRD42 (28% identical).
Diseases named in the same sentence as ANKRD37 in open-access papers:
ANKRD37 is named in the same sentence as 10 diseases in open-access papers, as found by Europe PMC text mining. Sharing a sentence is not in itself a finding about the gene and the disease. The quoted sentences say what the papers report.
preeclampsia (5 papers, 2014 to 2025). Preeclampsia is a hypertensive disorder of pregnancy that is characterized by new-onset hypertension with proteinuria presenting after 20 weeks of gestation, and depending on mild or severe forms may initially present with severe headache, visual disturbances, and hyperreflexia. "In order to further understand the role of screened biomarkers in the diagnosis and prediction of preeclampsia, we based on the nomogram model of four key genes: ANKRD37, CRH, LEP, and SIGLEC6." (PMID 38894741, 2024). "In vitro studies suggest that ANKRD37 plays a crucial role in the hypoxia response and may contribute to the development of preeclampsia under hypoxic conditions." (PMID 41141914, 2025). "ANKRD37 has no known role on macrophage activity and has been related to trophoblast migration and preeclampsia risk during pregnancy." (PMID 35619054, 2022). "In our single-cell analysis, ANKRD37 localized to extravillous trophoblasts with minimal expression in placenta accreta but relatively high expression in early onset preeclampsia, highlighting that this gene may be involved in minimizing the degree of placental attachment to the maternal decidua." (PMID 41141914, 2025). "In comparison with the normal control group, the expression levels of the candidate genes ANKRD37, CRH, LEP, and SIGLEC6 in preeclampsia placenta were significantly increased, as visualized by the boxplot function." (PMID 38894741, 2024). "From the heatmap, it can be observed that the expression of ANKRD37, CRH, LEP, and SIGLEC6 in preeclampsia placenta is significantly increased." (PMID 38894741, 2024). "Employing weighted gene co-expression network analysis (WGCNA) and lasso regression, four potential target genes (ANKRD37, CRH, LEP, SIGLEC6) are identified for potential prediction of preeclampsia." (PMID 38894741, 2024). "In this study, we observed that ANKRD37 and PFKFB3 exhibited hypomethylation and high expression in HTR‐8/SVneo cells after hypoxia, and they also showed low methylation in preeclampsia placental tissues." (PMID 38899809, 2024). "By integrating our previous data on DNA methylation from preeclamptic placental tissues, we identified that the ANKRD37 and PFKFB3 genes may contribute to the pathogenesis of preeclampsia through DNA methylation‐mediated transcriptome expression under hypoxic conditions." (PMID 38899809, 2024).
Iron deficiency (3 papers, 2018 to 2022). "Cu treatment of the basolateral side of cells significantly reduced DMT1, FPN, and TFR, and ANKRD37 mRNA levels under the iron deficiency condition." (PMID 36494833, 2022). "A significant decrease in theanemic condition in caco-2 cellswas observed by looking at the mRNA levels of marker genes (divalentmetal transporter-1 (DMT1), transferrin receptor (TFR), and ankyrinrepeat domain 37 (ANKRD37)) that were induced by iron deficiency anemia." (PMID 35755397, 2022). "mRNA regulation of Ankyrin repeat domain 37 (ANKRD37), prolyl 4-hydroxylase (P4ha1), and HIF prolyl hydroxylase 3 (EGLN3) are the most well-known marker genes for the hypoxic signal under iron deficiency." (PMID 36494833, 2022). "In the current study, we selected marker genes that were regulated by iron deficiency including iron transporters (DMT1, TFR, and FPN) and iron-dependent hypoxic genes (ANKRD37 and EGLN3)." (PMID 36494833, 2022).
glioblastoma (2 papers, 2014 to 2017). The most malignant astrocytic tumor (WHO grade IV). "These include previously identified HIF-1 target genes such as ANKRD37, STC-2, and STC-1, as well as COL5A1 induced by hypoxia in the ventricle, ZNF395 regulated by hypoxia in glioblastoma, and TMEM45 in hematopoietic stem cells." (PMID 25122487, 2014).
Anxiety (1 paper, 2024). Intense feelings of nervousness, tension, or panic often arise in response to interpersonal stresses. "Interestingly, some of the linear dose-response DEGs have been implicated in transmission and plasticity (GRIN2A, GAD2), depression and antidepressant effect (DDIT4, GAD2) anxiety and stress responses (ADCYAP1R1), WNT signalling (FRZB), neurogenesis (ARHGEF39) and hippocampal volume (ANKRD37)." (PMID 39055655, 2024).
depression (1 paper, 2024). "Citalopram exposure induced changes in ANKRD37 and GDF11, important for hippocampal volume, Interestingly, in mice, infusion of GDF11 enhanced hippocampal neurogenesis and attenuated depression-like symptoms." (PMID 39055655, 2024).
E. coli infection (1 paper, 2016). "We found that lnc-ANKRD37-1, lnc-CDC6-3, lnc-C5-1, lnc-BIRC3-1 and lnc-RP11-582J16.5.1-2 were upregulated in all of these three cell lines (by ≥2-fold), but exhibited responses of various intensities to meningitic E. coli infection." (PMID 27958323, 2016).
tumor (2 papers, 2011 to 2025). "Ankrd37 (ankyrin repeat domain 37) gene expression could be activated under hypoxia via the Hif-1a-dependent pathway, affecting autophagy, cell survival, and tumor progression." (PMID 41009560, 2025).
cancer (1 paper, 2014). A tumor composed of atypical neoplastic, often pleomorphic cells that invade other tissues. "ANKRD37 and AFAP1L1 in the ‘hypoxic group’ have been shown to be involved in migration and invasion of cancer cells." (PMID 25079072, 2014).
ANKRD37 also shares sentences with these, for which no sentence is quoted: pancreatic cancer (2 papers); iron deficiency anemia (1).